BDNF (brain derived neurotrophic factor)
Diseases named in the same sentence as BDNF in open-access papers (continued):
Sharing a sentence is not in itself a finding about the gene and the disease.
Anxiety (continued). "Hippocampal expression of BDNF and serotonin receptor 5HT1A are frequently related to emotion and anxiety-like behaviour Serotonin receptors receive input from neurons of the dorsal and ventral raphe nucleus plays an important role in anxiety-like behaviours." (PMID 36422338, 2022). "Does the low-anxiety phenotype observed in cKO mice depend on alterations of the BDNF-TrkB system?" (PMID 35140204, 2022). "These last data are important because a reduction in anxiety-like behaviors in the elevated plus maze (EPM) test was related to high levels of BDNF, which was accompanied by greater expression of TrkB and BDNF mRNA in brain structures such as the HP, PFC, and amygdala." (PMID 35684488, 2022). "High prenatal androgen excess may lead to dysregulation of neuropeptide Y, parvalbumin, and BDNF, leading to increased anxiety-like behavior." (PMID 36159923, 2022). "In addition, NYT was found to improve hippocampal BDNF levels and ameliorate anxiety and depressive-like behavior." (PMID 36299904, 2022). "Low-anxiety rats displayed higher BDNF mRNA levels than control animals (p = 0.008)." (PMID 36012411, 2022). "We found PD carriers of BDNF Met/Met were more sensitive to anxiety." (PMID 35815047, 2022). "Taken together, the elevation of hippocampal BDNF gene mRNA expression as well as the increase in PEA levels in low-anxiety rats might be considered markers of resilience to PS exposures." (PMID 36012411, 2022). "The results of the present study indicated that the level of BDNF, a neurobiological marker for anxiety, was increased in response to CLB treatment, which had an anxiolytic effect on behaviors and decreased the level of TNF‐α in the hippocampus in winning mice." (PMID 34878231, 2022). "The restoration of BDNF improved fear extinction and anxiety-like symptoms." (PMID 35722162, 2022). "In healthy meditation naïve females, even a short period of MBI may increase serum BDNF and reduce anxiety more than relaxation on-site." (PMID 35757176, 2022). "LZU-J-TSL6 was able to effectively increase the GABA content in the mice hippocampus (p < 0.0001) and restore some markers related to anxiety such as brain-derived neurotrophic factor (BDNF), glial fibrillary acidic protein (GFAP), and 5-hydroxytryptamine (5-HT)." (PMID 36429192, 2022). "The mechanism underlying the anti-anxiety-like effect of gelsemine may be to protect neurons by suppressing the occurrence and development of inflammation by modulating the NLRP3 and CREB/BDNF pathways." (PMID 35203954, 2022). "In addition, in vitro results of the extruded WB samples showed degradation of phytate, which increased the solubility and absorption of minerals present in WB, which can be relevant for the regulation of the HPA-axis, anxiety, and BDNF levels." (PMID 35694161, 2022). "Animal models suggest that variations in BDNF expression may be mirrored in impairments of learning, memory, and social behavior, including anxiety-like traits." (PMID 35911240, 2022). "Moreover, a complete mediation by the BDNF CpG6 methylation emerged between pandemic-related stress during pregnancy and postnatal maternal anxiety, ACME = 0.66, p < 0.05." (PMID 35911240, 2022). "Furthermore, in SMs, the decrease in the BDNF gene expression correlated with higher anxiety and the increase in the BDNF gene expression correlated with lower anxiety." (PMID 36498900, 2022). "BDNF is known to be related to anxiety as well as cognitive functions." (PMID 35563336, 2022). "Reduction in BDNF and GABA neurotransmission co-occur in the mPFC tissues and has been repeatedly seen in animal models and human subjects, and this has been associated with anhedonia and anxiety." (PMID 34674715, 2021).
Anxiety (continued). "For instance, in the direct route, Bercik showed that B. longum NCC3001 could normalize the anxiety-like behavior in gut chronic inflammation mice by innervating vagal afferent terminals, resulting in the upregulation of BDNF in the neural cells of the brain." (PMID 35070442, 2021). "This hypothesis is supported by earlier studies showing that the BDNF pathway is affected by various drugs of abuse, it is involved in the expression of anxiety-like behaviors and is strongly related to excessive alcohol-drinking and relapse." (PMID 33671048, 2021). "Hence, music has been suggested as an effective contribution to therapeutic intervention for psychiatry disorders, thanks to its regulation of BDNF levels, which are of essential importance to regulate mood and reduce anxiety." (PMID 33477654, 2021). "We also demonstrated that oxytocin could ameliorate the adverse effects of EE on anxiety and social behaviors and normalized plasma BDNF levels." (PMID 33503967, 2021). "Importantly, both GABAergic synapse and neurotrophic signaling pathways (BDNF-Ntrk2) were involved in the antidepressant and anti-anxiety effects of the LBRD standard decoction in both in vitro and in vivo models." (PMID 34674715, 2021). "However, maternal symptoms of anxiety correlated with significantly raised maternal serum BDNF exclusively in mothers of boys (r = 0.281; P = 0.005; n = 99)." (PMID 33462179, 2021). "In conclusion, reserpine administration induces depressive and anxiety-like behaviors, increasing corticosterone and pro-inflammatory cytokines in the plasma and hippocampus, respectively, and decreasing hippocampal pCREB/BDNF expression." (PMID 34220460, 2021). "BDNF upregulation in SERT−/− rats normalized the level of anxiety to that of SERT+/+ rats." (PMID 34068707, 2021). "Furthermore, AChE-R overexpression was associated with increased expression in anxiety-related genes, i.e., BDNF’s proteolytic activator MBTP1, BDNF’s receptor and BDNF’s coactivator of mitogen-activated protein kinase, PTPN11." (PMID 34502198, 2021). "Although the wheel activity itself seems to lower anxiety in rats previously exposed to stressful conditions, BDNF levels increased in the striatum and anxiety, measured by the open field test, turned out to be positively correlated with RWA in the food restriction phase of the ABA protocol." (PMID 34600568, 2021). "Stress hormone binding to the GR downregulates BDNF and induces anxiety-like behaviors." (PMID 34698102, 2021). "A recent report showed that alterations in p-CREB/CREB and BDNF expression in stress-induced anxiety-like behaviours could be regulated by dammarane sapogenin treatment." (PMID 34646421, 2021). "Alternatively, under conditions of maternal anxiety, the male fetus or placenta may produce signals driving elevations in maternal BDNF." (PMID 33462179, 2021). "However, it should be noted that only hippocampal BDNF overexpression attenuated anxiety-like behaviors." (PMID 34769417, 2021). "Anxiety and depressive behaviors in humans have been linked with social stress that, when modeled in animals, is associated with changes both in HPA axis function and a down-regulation of BDNF protein and mRNA expression in the hippocampus." (PMID 33578758, 2021). "Moreover, exposure to music in the juvenile age results in a notable increase in BDNF expression that can protect in later stressful events, thus preventing anxiety-like behaviors." (PMID 33477654, 2021). "Low serum BDNF levels were found in RA patients with anxiety or receiving biologics treatment." (PMID 33673283, 2021). "Interestingly, decreases in hippocampal TNF and IL-6 levels were observed in a murine eCM model with cannabidiol treatment, which also increased brain derived neurotrophic factor levels, promoted eCM survival and prevented post-CM anxiety-like behaviours." (PMID 32703204, 2020).
Anxiety (continued). "Inflammatory signalling, such as increased brain-cortical TNF levels in conjunction with either increased IL-6 or IL-1β, and alterations in growth factor levels, e.g. brain derived neurotrophic factor and neuregulin, can contribute to the development of anxiety in eCM and behavioural sequelae." (PMID 32703204, 2020). "Moreover, plasma levels of BDNF and NT-4 were correlated with anxiety (r = −0.262, p = 0.028; r = −0.258, p = 0.030) as measured by the SAS; nevertheless, the difference was no longer significant after Bonferroni correction." (PMID 32210759, 2020). "Exercise intervention may regulate the stress response through the HPA axis or glucocorticoid circulation, increasing cell proliferation and levels of brain-derived neurotrophic factor responsible for reducing anxiety." (PMID 33192853, 2020). "Thus, QUER has demonstrated that adequate modulation of BDNF and iNOS can significantly alleviate LPS-induced anxiety-like behaviors." (PMID 32419805, 2020). "It was reported that the anxiety disorder caused by alcohol withdrawal is related to a decrease in the expression of BDNF, and micro-infusion of BDNF in the central nucleus of the amygdala not only reduces ethanol consumption but also reverses the anxiety induced by ethanol withdrawal." (PMID 32508571, 2020). "This study examined the effects of SWHP on ameliorating anxiety-like behaviors by regulating endocannabinoids system (ECS)—brain-derived neurotrophic factor (BDNF)—extracellular regulated protein kinases (ERK) signaling pathway expression, induced by restraint stress (RS) procedures." (PMID 32655658, 2020). "In a light/dark exploration test on BDNF conditional mutant mice, the absence of central BDNF caused higher levels of anxiety and hyperactivity after exposure to stressors in these mutant mice." (PMID 33047489, 2020). "However, RG and fRG suppressed IS- or EC-induced anxiety/depressive behaviors, NF-κB activation, and NF-κB+/Iba1+ cell population and increased the BDNF expression and BDNF+/NeuN+ cell population in the hippocampus." (PMID 32224881, 2020). "Since BDNF is involved in the induction of anxiety-like symptoms in the hippocampus, regulation of BDNF signaling may be an important factor in the anxiety-like behavior of rats induced by LPS injection." (PMID 32419805, 2020). "Early evidence suggests that through post-fermentation by resident gut microbiota, prebiotics are capable of modulating a central brain growth factor (BDNF) among other plasticity-related proteins, neurotransmitters, cytokines, as well as anxiety, and emotional processing." (PMID 32093203, 2020). "We simultaneously performed western blotting and immunohistochemical analyses to explore possible mechanisms involving BDNF signaling that may be fundamental in the anti-anxiety effects of SYG, CHA, and Mix." (PMID 33097741, 2020). "Physical activity might reduce anxiety/depressive symptoms through a variety of psychosocial and biological mechanisms, such as increasing neurotrophic factor (BDNF) and endogenous opioids (endorphins), improving the immune system, or promoting self-esteem." (PMID 33329238, 2020). "Anxiety in early-weaned mice was ameliorated by pretreatment with BDNF or a BDNF receptor agonist." (PMID 30850750, 2019). "Our data also suggest that upregulated BDNF may participate in the promotion of conditioned fear extinction and the reduction of anxiety-like behaviors." (PMID 31380440, 2019). "This suggests that epilepsy changes the general rule linking anxiety and serum BDNF levels." (PMID 31331937, 2019). "Our findings thus suggested that the differential expressions of BDNF and IL-6 after CSDS may contribute to less anxiety and less despair observed in GHS-R1a-deficient mice than in WT control mice." (PMID 31057357, 2019). "Finally, we found that 4) pharmacologically activating PFC BDNF signaling ameliorated anxiety in the early-weaned mice." (PMID 30850750, 2019).
Anxiety (continued). "Likewise, only the interaction of 5HTTLPR and BDNF contributed significantly to anxiety (Beta = −4.51, t = −2.30, p = .024), accounting for approximately 4.97%–5.24% of the variance in rating scores for this symptom." (PMID 31440532, 2019). "Furthermore, Nrf2 knockdown by a short hairpin RNA affected anxiety-like behaviors and expression of neuroprotective markers (BDNF, DCX) in a manner similar to ESPS alone and dampened the neuroprotective effects of EA pretreatment." (PMID 31293390, 2019). "For example, child brain-derived neurotrophic factor (BDNF) genotype was found to moderate effects of maternal prenatal anxiety on later child internalizing problem behavior, as well as on the child’s epigenome and structures of the amygdala and the hippocampus." (PMID 31316398, 2019). "However, contrast results have been reported in the female mouse brain in which social isolation-induced anxiety-like behavior is mediated by the upregulation of mRNA and protein levels of BDNF in the cerebral cortex." (PMID 29325565, 2018). "Accordingly, heterozygous BDNF knock-out animals show anxiety-like behavior or signs of obesity." (PMID 30319348, 2018). "In most studies examining, BDNF levels were elevated following exposure to music, and this might explain the reduced anxiety." (PMID 30618659, 2018). "Therefore, GPS dose-dependently mitigated LPS-induced anxiety-like behaviors via appropriate modulation of NF-κB/TLR4/BDNF." (PMID 30460112, 2018). "Additionally, HCN1-related BDNF played a crucial role in the pathogenesis of anxiety were explored in our previous study which found there was a negative correlation between the level of BDNF and HCN1 in the brain." (PMID 29896126, 2018). "Furthermore, transplantation of gut microbiota or Bifidobacteria into germ-free mice suppressed anxiety-like behaviors and up-regulated brain-derived neurotrophic factor (BDNF) expression in the hippocampus." (PMID 30224732, 2018). "A low serum level of BDNF is a biomarker of anxiety and memory disorders." (PMID 30002347, 2018). "Moreover, the genetic overexpression of the BDNF mature isoform in female mice impaired working memory functions, reduced breeding efficiency, increased anxiety-like behaviors, impaired prepulse inhibition, and elicited higher susceptibility to seizures." (PMID 29867348, 2018). "The major finding of this study is that seven days of RS, already reported to promote anxiety/depressive-like phenotype in heterozygous BDNF Val66Met (BDNFVal/Met) mice, are sufficient to exacerbate arterial thrombosis in BDNFVal/Met mice and enhance platelet activation and coagulation pathway." (PMID 30347685, 2018). "Both in models and humans, stress, fear and anxiety are associated with enhanced rather than lowered serum levels of BDNF and NGF." (PMID 28068360, 2017). "Considering that these brain regions are involved in mood and anxiety, changes of BDNF expression in these brain regions may mediate the effects of gravity changes on mood and anxiety directly or indirectly." (PMID 28591153, 2017). "In the current study, we found that those scoring higher on the BSI anxiety scale (both at pre- and post-testing) tended to demonstrate a less robust increase in BDNF levels, consistent with the notion that BDNF levels were indeed related to psychological wellness." (PMID 28694775, 2017). "Among the studies which found decreased BDNF expression, increased anxiety-like behavior (such as shorter time spent in the open arms of an elevated plus maze or longer latency to feed in the novelty suppressed feeding test) was reported in 4/6 studies (unchanged in 1/6, decreased in 1/6)." (PMID 28620285, 2017). "Mice, subjected to IFS, exhibited anxiety-like behavior and fear relapse, accompanied by the increased levels of DNA methyltransferases, hyper-methylation of Bdnf gene, and decreased BDNF mRNA expression in the medial prefrontal cortex (mPFC) and hippocampus (HIP)." (PMID 28473755, 2017).
Anxiety (continued). "Summarizing, irisin may contribute to BDNF's ability to influence mood and anxiety by altering contextual learning in structures under BDNF control thus induce the evolution of distress disorder." (PMID 29217995, 2017). "We found that women who were carriers of the BDNF rs6265 Met allele exhibited a negative association between the right amygdala-vPFC pathway and anxiety." (PMID 28887539, 2017). "Moreover, intra-CeA infusion of BDNF attenuated anxiety-like behaviors that developed during ethanol withdrawal in rats." (PMID 27303256, 2016). "Both F1 females and males from restrained mothers and/or fathers showed significantly reduced anxiety and serum cortisol and increased mRNA levels of glucocorticoid receptor and brain-derived neurotrophic factor compared to control offspring from unstressed parents." (PMID 28000794, 2016). "Correspondingly, anxiety symptoms were associated with the BDNF risk genotype only in BD offspring but not in healthy controls, and BD offspring with the val/val genotype showed higher anxiety symptoms than BD offspring with other genotypes." (PMID 27867834, 2016). "In mice, social deprivation, which may be similar to the depressed maternal care experienced by CSS F2 rats when young, decreases BDNF levels in the brain and increases anxiety." (PMID 34055816, 2016). "The present study was conducted to determine whether an impaired hippocampal BDNF system underlies facilitated CCER that is associated with inhibited temperament and anxiety vulnerability." (PMID 26257661, 2015). "Thus, low levels of BDNF protein or impaired BDNF release via a Val66Met SNP results in a smaller hippocampus, abnormal fear extinction, anxiety-related behaviors, and reduced efficacy of antidepressants." (PMID 26257661, 2015). "BDNF has also emerged as a potential biomarker for anxiety from preclinical studies in rodents." (PMID 25734326, 2015). "Other authors have found that, in rats, a BDNF antisense oligodeoxynucleotide (which reduces BDNF gene expression) provokes anxiety-like behaviors when infused into the central and medial amygdala, but not basolateral amygdala, and that these effects are rescued by BDNF co-infusion." (PMID 25932008, 2015). "Furthermore, reduction of BDNF in the hippocampus and cortex is also involved in HFD (60 kcal% fat)-caused depressive- and anxiety-like behaviors." (PMID 25309465, 2014). "The DSS-induced behavioral syndrome comprises a reduction of locomotion and exploration, an apparent increase in anxiety and a decrease in social activity and is associated with enhanced expression of COX-2 in the hypothalamus and attenuated expression of BDNF, NPY, and MR in the hippocampus." (PMID 25414650, 2014). "Keeping this in mind, the slightly reduced BDNF levels in the frontal cortex only could be a consequence of the Creb ablation but are an insufficient explanation for the altered anxiety levels seen in the Creb mutants analyzed here." (PMID 25505876, 2014). "So, our study supported the previous reports further and BDNF signaling might play important roles in high cholesterol diets induced changes of anxiety-like behavior in rats." (PMID 25179125, 2014). "BDNF levels appear to play an important role in Creb-dependent regulation of emotional behavior, since peripherally administered BDNF was observed to increase pCREB and, in parallel, to reduce anxiety." (PMID 25505876, 2014). "Neuronal release of BDNF can alter anxiety-like behaviors in mice and age-dependent changes in the expression of BDNF observed in the brain of Fmr1 KO mice could at least partially explain the alterations seen in the anxiety phenotype in different studies." (PMID 24904293, 2014). "In animal models, BDNF depletions provoked anxiety-like behaviors, resulting in increased alcohol intakes, which could be rescued by BDNF co-infusion." (PMID 26501066, 2014).